PEX39 (peroxisomal biogenesis factor 39)
Description:
Cytosolic peroxin that promotes the peroxisomal import of proteins containing a type-2 peroxisomal targeting signal (PTS2) by binding to PEX7 and stabilizing its interaction with PTS2-containing cargo. PEX39 subsequently transfers the PEX7-cargo complex to PEX13 at the peroxisomal membrane, enabling PEX7 to bind PEX13 and facilitating translocation of PTS2-containing proteins into the peroxisome. Both PEX39 and PEX13 contain a conserved KPWE motif, which enables competitive binding to PEX7 and ensures efficient handover of the complex.
Synonyms: C6orf226; LOC441150
Tractability: No criterion of Open Targets' tractability assessment is met for any kind of drug.
Gene: Protein-coding gene on chromosome 6 (42,890,265 to 42,890,821, reverse strand). Ensembl gene ENSG00000221821.
Subcellular location: Cytoplasm, cytosol
Subcellular location (Human Protein Atlas): Nuclear speckles
Gene Ontology:
Molecular function: peroxisome targeting sequence binding; protein binding
Biological process: protein import into peroxisome matrix, docking
Cellular component: cytosol
Genetic constraint (gnomAD): Loss-of-function variants: 3 observed, 1.06 expected, observed/expected ratio (o/e) 2.84. That is too few expected variants to judge how well the gene tolerates losing a copy. Missense variants: 163 observed, 142.72 expected, observed/expected ratio (o/e) 1.14, 90% interval 1 to 1.3. Synonymous variants: 88 observed, 68.78 expected, observed/expected ratio (o/e) 1.28, 90% interval 1.08 to 1.53.
Homologues: Orthologues: chimpanzee C6H6orf226 (97% identical), mouse Pex39 (50% identical), rat C9h6orf226 (48% identical).
Diseases named in the same sentence as PEX39 in open-access papers:
PEX39 is named in the same sentence as 2 diseases in open-access papers, as found by Europe PMC text mining. Sharing a sentence is not in itself a finding about the gene and the disease. The quoted sentences say what the papers report.
peroxisomal disease (1 paper, 2025). A group of congenital disorders of lipid metabolism, caused by loss of the normal peroxisomes. "Collectively, this work reveals how PEX39 and (R/K)PWE motifs facilitate the import of PTS2-containing proteins and advances our understanding of peroxisomal disease." (PMID 40739340, 2025).
PEX39 also shares sentences with these, for which no sentence is quoted: colon cancer (1 paper).